PLCB1 (phospholipase C beta 1)
Diseases named in the same sentence as PLCB1 in open-access papers (continued):
Sharing a sentence is not in itself a finding about the gene and the disease.
glioma (9 papers, 2013 to 2024). A benign or malignant brain and spinal cord tumor that arises from glial cells (astrocytes, oligodendrocytes, ependymal cells). "In summary, our data analyses of TCGA and four independent GEO datasets revealed an association between differential expression of PLCβ1 and glioma pathological grades." (PMID 26614510, 2016). "Specifically, we found an association of miR-34a with phospholipase C (PLCB1), which has recently been identified as a regulator of glioma cell migration." (PMID 23358700, 2013). "Additionally, neuronal levels of PLCβ1 are negatively associated with the presence and aggressiveness of gliomas." (PMID 38789419, 2024). "PLCβ1 expression decreased in a malignancy-dependent manner in gliomas, and the level of PLCβ1 expression was significantly correlated with the survival rate." (PMID 37371495, 2023). "In particular, it was demonstrated that PLCβ1 gene expression was inversely correlated with the pathological grade of gliomas and that patients with intermediate PLCβ1 expression had a higher chance of survival than the PLCβ1-downregulated group." (PMID 37238668, 2023). "Based on all these results, we concluded that glioblastoma was characterized by an overall reduced PLCβ1 expression compared to healthy samples and low-grade gliomas." (PMID 35303162, 2022). "Glioblastoma is characterized by reduced PLCβ1 gene expression compared to both low-grade gliomas and healthy patients." (PMID 35303162, 2022). "In particular, an inverse correlation between PLCβ1 gene expression and glioma pathological grade has been highlighted, suggesting PLCβ1 as a potential prognostic factor and a potential novel signature gene for the classification of HGG." (PMID 35303162, 2022). "What emerged from the first analysis was the inverse correlation between the expression of PLCβ1 and the pathological grade of gliomas." (PMID 35303162, 2022). "This study aims to determine the pathological impact of PLCβ1 in glioblastoma, confirming that PLCβ1 gene expression correlates with glioma’s grade, and it is lower in 50 glioblastoma samples compared to 20 healthy individuals." (PMID 35303162, 2022). "Several studies have shown the key role of phospholipase C β1 (PLCβ1) in the regulation of many mechanisms within the central nervous system suggesting PLCβ1 as a novel signature gene in the molecular classification of high-grade gliomas." (PMID 35303162, 2022). "These stains from human gliomas demonstrate that astrocytes can be induced to express PLCβ1 under pathological conditions." (PMID 26614510, 2016). "When PLCβ1 expression is further stratified as 3X, 4X, 5X, 6X, and 7X downregulation in glioma cases, log-rank tests still show significant differences between intermediate and downregulated groups." (PMID 26614510, 2016). "PLCβ1 originating from glioma cells, if there is any, only contributes partially to measurable PLCβ1 gene expression." (PMID 26614510, 2016). "Grouping with the listed PN signature genes makes PLCβ1 another candidate signature gene for PN subtype glioma." (PMID 26614510, 2016). "PLCβ1 expression is significantly higher in grade III gliomas than that in grade IV gliomas from GDS1815 (n = 24 vs. 76), GDS1962 (n = 19 vs. 81), and GDS1975 (n = 26 vs. 59)." (PMID 26614510, 2016). "In GDS1815, when combining data from grade III and IV glioma, PLCβ1 level is significantly different between two groups of patients: <2 years (n = 48) vs. over 2 years survival (n = 35)." (PMID 26614510, 2016). "The detected PLCβ1 level from gliomas is possibly a logical reflection of residual neurons’ PLCβ1 content, which will diminish as the tumor cells expand." (PMID 26614510, 2016). "This raises the possibility that overall PLCβ1 signal from glioma tumors is mainly determined by residual neurons, which harbor much higher levels of PLCβ1 than other cell types." (PMID 26614510, 2016).
glioma (continued). "PLCβ1 gene expression inversely correlate with tumor grades (III and IV) and survival among glioma patients in GDS1815 dataset, the presence of PLCβ1 transcripts are associated with PN subtype GBM from Mes and proliferative subtypes." (PMID 26614510, 2016). "Phospholipase C beta 1 (PLCβ1) expresses in gliomas and cultured glial cells, but its expression is barely detectable in normal glial cells." (PMID 26614510, 2016). "When analyzing PLCβ1 expression level in glioma subclass, astrocytoma cases are stratified into intermediate (n = 48) and downregulated (≥2X) groups (n = 57); there is no upregulated group." (PMID 26614510, 2016). "In GDS1975, PLCβ1 expression was also significantly lower in grade IV (n = 59) than in grade III gliomas (n = 26, p = 0.3.0E-6)." (PMID 26614510, 2016). "In combined samples of grade III and IV gliomas, the average PLCβ1 signal level in PN subtypes (2642 ± 207, n = 37) is still significantly higher than its level in Mes (852 ± 120, n = 35) and in proliferative subtypes (1242 ± 170, n = 28; both p < 0.05)." (PMID 26614510, 2016). "We analyzed data from Gene Expression Omnibus (GEO-GDSxxx), The Cancer Genome Atlas (TCGA), and the Repository for Molecular Brain Neoplasia Data (REMBRANDT) to explore the potential role of PLCβ1 as a biomarker in high-grade glioma (HGG)." (PMID 26614510, 2016). "The top 50 % of PLCβ1 expression subgroup (n = 294) of gliomas (grades II to IV merged) survived significantly longer than the low 50 percentile of the PLCβ1 expression subgroup (n = 293)." (PMID 26614510, 2016). "Normalized PLCβ1 expression inversely correlates with pathological grades of glioma: the higher the pathological grade, the lower the PLCβ1 expression (p < 0.0001)." (PMID 26614510, 2016). "Log-rank test results show significant differences between the intermediate PLCβ1 group and the PLCβ1 downregulated groups for glioma (p = 3.0E-09) and its subclass astrocytoma (p = 2.0E-04) in a Kaplan-Meier survival plot." (PMID 26614510, 2016). "Rodent studies showed that PLCβ1 expression is undetectable by PCR from freshly isolated astrocytes, but it can be detected in established astrocytoma cell lines and C6 rat glioma cell lines." (PMID 26614510, 2016). "Glioma samples show unidirectional reduction regarding PLCβ1 expression—the higher the pathological grade, the lower the level of PLCβ1 expression (microarray and RNA-Seq data)." (PMID 26614510, 2016). "PLCβ1 level in gliomas was not only useful in the separation of low- and high-grade astrocytomas, but also has significant differences between grades II (low-grade) and III (high-grade) oligodendrogliomas." (PMID 26614510, 2016). "It is possible that ERBB4 and PLCβ1, as neuron predominant proteins, contribute to glioma tumorigenesis or progression." (PMID 26614510, 2016). "We further validated the relationship between PLCβ1 expression and gliomas’ pathological grades using other three independent GEO datasets (GDS2853, GDS1962, GDS1975)." (PMID 26614510, 2016). "A Kaplan-Meier survival curve from a REMBRANDT cohort demonstrates that glioma patients with intermediate PLCβ1 expression (n = 103) survived significantly longer than PLCβ1 downregulated (2X) groups (n = 226)." (PMID 26614510, 2016). "In addition, a study based on data analysis of the Cancer Genome Atlas (TCGA) and from Gene Expression Omnibus, revealed the potential role of PLCβ1 as biomarker in high-grade gliomas (HGG)." (PMID 35303162, 2022). "All in all, in silico data from database, clinical data collected on glioblastoma fresh-frozen samples, together with cellular and molecular data on engineered immortalized and primary cell lines, suggest a potential role of PLCβ1 in maintaining a normal or less aggressive phenotype of glioma." (PMID 35303162, 2022). "Moreover, in the same study, it was demonstrated that glioma patients with intermediate PLCβ1 expression survived significantly longer than PLCβ1 downregulated group." (PMID 35303162, 2022).
glioma (continued). "Indeed, WHO IV gliomas showed a lower gene expression of PLCβ1 compared to WHO II and III gliomas, confirming data already present in literature." (PMID 35303162, 2022). "In addition, our analysis demonstrates that PLCβ1 gene expression level correlates the best with glioma PN signature gene ERBB4." (PMID 26614510, 2016). "We hypothesize that PLCβ1 could be a signature gene in glioma subclassification given its absence in normal glial cells, yet presence in glioma specimens." (PMID 26614510, 2016). "Accumulating evidence suggests a pathological role of PLCβ1 in glioma abnormality." (PMID 26614510, 2016). "Glioma are stratified into groups based on PLCβ1 expression: 103 cases in the intermediate group, 226 cases in the downregulated (≥2X) group, and 0 cases in the PLCβ1 upregulation (≥2X) group." (PMID 26614510, 2016). "Thus, the finding that PLCβ1 expression was detected in glioma tissues by different methods such as microarray, RNA-Seq, and IHC indicates a very meaningful and possibly a pathological change." (PMID 26614510, 2016). "However, some glioma samples are stained with PLCβ1 antibodies, both cytoplasmic and inside nucleus." (PMID 26614510, 2016). "Thus, we summarize this inverse relationship between PLCβ1 expression and glioma pathological grades in diagram." (PMID 26614510, 2016). "Furthermore, Kaplan–Meier survival curves from CGGA dataset, demonstrated that patients with low- or high- grade gliomas, characterized by a low expression of PLCβ1, have a shorter survival time in both primary and recurrent gliomas compared to patients with high-PLCβ1 expression." (PMID 35303162, 2022). "Interestingly, this study confirmed that PLCβ1 gene expression was significantly reduced in all WHO IV gliomas (glioblastoma), not only in specific subtypes, compared to WHO II and WHO III gliomas, suggesting a strongly pathological role of PLCβ1 low expression." (PMID 35303162, 2022). "In addition, the results of the survival analysis carried out with the CGGA database indicated that patients with low- or high- grade glioma, characterized by a low expression of PLCβ1 have a shorter survival time in both primary and recurrent gliomas compared to patients with high-PLCβ1 expression." (PMID 35303162, 2022). "Similarly, miR‐423‐5p directly targets PLCB1 expression in glioma to inhibit tumor cell metastasis." (PMID 33174687, 2020). "Thus, it will be necessary to study cellular origins of PLCβ1 expression in gliomas to determine if different levels of PLCβ1 expression actually originate from oligodendrocytes, astrocytes, or even possibly mesenchymal cells versus normal and abnormal neuroprogenitor cells, or neurons." (PMID 26614510, 2016). "To perform PLCβ1 gene expression study, we first examined the CGGA online public database containing PLCβ1 RNA-seq and survival data of patients with different glioma grades (from II to IV)." (PMID 35303162, 2022). "For example, MiR‐423‐5p inhibits glioma metastasis by targeting phospholipase C beta 1 (PLCB1) via the ERK‐dependent pathway, and also promotes apoptosis in glioma cells." (PMID 33174687, 2020). "It affects the occurrence and development of glioma by regulating a series of tumor-related genes, such as FEN1, CCL3, PLCB1, NRAS and PIK3s, and activation of apoptosis signaling pathways." (PMID 29033691, 2017). "Overall, this study indicated that PHF20 is a pivotal upstream gene that influences the occurrence and development of glioma by regulating a series of tumor-related genes, like FEN1, CCL3, PLCB1, NRAS and PIK3s, and involved in apoptosis signaling pathways." (PMID 29033691, 2017). "A Kaplan-Meier survival curve of both REMBRANDT [glioma and astrocytoma] and TCGA data [grade II to IV merged and GBM] showed that different subgroups of PLCβ1 microarray/RNA-Seq expression levels correlate well with patient survival (p < 0.05)." (PMID 26614510, 2016).
glioma (continued). "We conclude that PLCβ1 is a candidate signature gene for PN subtype HGG, and its expression inversely correlates with glioma pathological grade and is a potential prognostic factor." (PMID 26614510, 2016). "In agreement with these two signature genes, PLCβ1 also shows a significantly different expression between grade III (n = 24) and grade IV (n = 76) gliomas (p < 0.001)." (PMID 26614510, 2016). "In GDS1962, PLCβ1 expression is the highest in nontumor brain tissue (n = 23) and is significantly higher than its expression in grade II gliomas [astrocytomas (n = 7) and oligodendrogliomas (n = 37)]." (PMID 26614510, 2016). "There are reports that glioma cell lines contain detectable PLCβ1; however, no information is available as to whether mesenchymal cells, despite being one of the common types of cells identified in glioma, express PLCβ1." (PMID 26614510, 2016). "PLCβ1 is a potential novel signature gene for PN subtypes in molecular classification of HGG because its gene expression correlates with known PN subtype signature genes; its inducible property in glial cells further supports its role as a biomarker in glioma classification." (PMID 26614510, 2016). "There have been no study found PLCβ1-mediated signaling in gliomas, and we speculate that PLCβ1 may play a role in glioma tumorigenesis." (PMID 26614510, 2016). "In addition, PLCβ1, while absent in freshly isolated normal glial cells, has been detected in C6 rat glioma cell lines." (PMID 26614510, 2016). "If the transcription of one PLCβ1 isoform is predominant isoform, the minor component of overall PLCβ1 signal may not contribute to our conclusion reached in this study: the higher the glioma grade, the lower the PLCβ1 expression." (PMID 26614510, 2016). "Quantitative PLCβ1 microarray/RNA-Seq result(s) could be incorporated with current molecular assay tools to supplement tradiational neuropathology in classifying HGG subtype(s), potentially contributing to glioma patient prognosis and measuring therapy effectiveness." (PMID 26614510, 2016). "The majority of reports show negative PLCβ1 staining in glioma cells; both HPA057910 and CAB004275 antibodies yield negative staining in glioma cells in 11 glioma samples (data not shown)." (PMID 26614510, 2016).
autism (8 papers, 2011 to 2023). Persistent deficits in social interaction and communication and interaction as well as a markedly restricted repertoire of activity and interest as well as repetitive patterns of behavior. "For example, in our cohort, one autism patient (#20) was carrying a 476-kb pathogenic deletion disrupting the PLCB1 gene." (PMID 36959829, 2023). "Hub genes of the turquoise module included one GABA receptor encoding genes such as Gabrb1, one glutamate receptor gene (Grid2) and genes tightly associated with synaptic development and autism (Nrxn1, Lrfn5, Plcb1, Erc2, Frmpd4, Tanc2, Ctnnd2, Dmd)." (PMID 34021132, 2021). "Because of the small LD region at 20p12.3, containing only a single locus, both the probability of genome-wide association and autism candidacy could be assessed for the same gene, thus clearly pointing to PLCB1 as a potential autism susceptibility locus." (PMID 24564958, 2014). "However, the co-location of population-based signals and autism susceptibility loci harbouring rare mutations, such as PLCB1, is unlikely to be due to chance (genome-wide empirical Pco-location = 0.007)." (PMID 24564958, 2014).
depression (8 papers, 2015 to 2024). "Plcb1-related signal pathway related to depression, and chronic treatment with quetiapine changed Plcb1 mRNA level from microarray analysis." (PMID 35771226, 2022). "The second module control downstream FOS to treat depression by targeting the DRD1/DRD5--GNAQ--PLCB1--DAG--PRKCA cascade reaction." (PMID 34867413, 2021). "Our results of enrichment analysis suggested that Plcb2 may be also one of depression-related target molecules like Plcb1." (PMID 35771226, 2022).
glioblastoma (8 papers, 2016 to 2024). The most malignant astrocytic tumor (WHO grade IV). "A 2016 in silico study showed PLCβ1 as a potential prognostic factor and a candidate signature gene for specific subtypes of glioblastoma." (PMID 37238668, 2023). "Recent findings highlighted an effective role of PLCβ1 in supporting a less aggressive phenotype of the tumor, demonstrating that its gene was relatively less expressed in glioblastoma patients compared to in their healthy/low-grade counterparts." (PMID 37238668, 2023). "After patients’ stratification, the reduction in PLCβ1 expression resulted to be statistically significant in 38 glioblastoma patients compared to healthy controls." (PMID 35303162, 2022). "This analysis confirmed that PLCβ1 expression is decreased in glioblastoma samples not only compared to low-grade tumors, but also compared to healthy individuals." (PMID 35303162, 2022). "To investigate the relation between PLCβ1 and glioblastoma, we silenced PLCβ1 in two different glioblastoma cell line models." (PMID 35303162, 2022). "It was highlighted an overall lower expression of PLCβ1 in glioblastoma samples compared to the healthy ones." (PMID 35303162, 2022). "These in silico data were strengthened by the retrospective analysis of PLCβ1 mRNA expression in 50 fresh-frozen glioblastoma tissue samples in comparison with 20 healthy individuals divided into 4 different pools." (PMID 35303162, 2022). "PLCB1 expression is also controlled by miRs, such as miR-3184 in hepatocellular carcinoma and miR-423-5p in glioblastoma cells." (PMID 34064422, 2021). "From TCGA data, PLCβ1 RNA-Seq signal inversely correlates with the pathological grades, and PLCβ1 expression in PN (n = 8) is of significantly higher levels than that in Mes (n = 8) subtypes of glioblastoma." (PMID 26614510, 2016). "The increased activation of this pathway, together with ERK1/2 and β-catenin pathways, reinforce the hypothesis that PLCβ1 downregulation in glioblastoma promotes a more aggressive phenotype." (PMID 35303162, 2022). "Subsequently, we analyzed PLCβ1 gene expression in 50 tissues from fresh-frozen retrospective glioblastoma patients of the last 10 years, compared to 4 healthy samples pools, each one containing total RNA derived from 5 different healthy donors, used as controls (20 patients in total)." (PMID 35303162, 2022). "Substantially, our glioblastoma models show how PLCβ1 silencing pushes towards cell survival." (PMID 35303162, 2022). "Indeed, following PLCβ1 silencing, it is also shown in our data, an increased activation of Stat3 pathway, which is a well-defined oncogenic transcription factor that plays a key role in tumor resistance and aggressive cancer progression in glioblastoma." (PMID 35303162, 2022). "PPI and gene ontology networks examined suggest the existence of further targets to be explored for the treatment of glioblastoma, such as PRKG1, CFTR, PLCB1, and TBX2." (PMID 27564115, 2016). "On the other hand, the higher PLCβ1 expression seen in the other 12 glioblastoma patients was not statistically relevant." (PMID 35303162, 2022).